DNMT1 (DNA methyltransferase 1)
Diseases named in the same sentence as DNMT1 in open-access papers (continued):
Sharing a sentence is not in itself a finding about the gene and the disease.
myeloid leukemia (11 papers, 2009 to 2023). A clonal proliferation of myeloid cells and their precursors in the bone marrow, peripheral blood, and spleen. "Aberrant DNA methylation mediated by mutations of TET2, WT1, DNMT1, DNMT3A, and DNMT3B genes is correlated to the pathogenesis of myeloid leukemia." (PMID 37375831, 2023). "Dnmt1 may be involved at the pre-leukemic stage of myeloid leukemias, as it is needed for the maintenance of HSCs and HPCs which are decreased in a zebrafish mutant cell line that has a stop codon mutation in Dnmt1." (PMID 34575830, 2021). "Here, we determined whether curcumin was able to induce hypomethylation in myeloid leukemia cells by down-regulating DNMT1 gene expression." (PMID 23457487, 2013). "Prior studies have shown that DNA methyltransferase (DNMT) genes, including DNMT1, are aberrantly overexpressed in myeloid leukemias." (PMID 29955131, 2019). "In the absence of CCDC26, DNMT1 is mis-localized in the cytoplasm, leading to DNA hypomethylation and apoptosis similar to that observed on inhibition of DNMT1 in myeloid leukemia cells." (PMID 33851096, 2021). "Transient expression of BCR-ABLp210 in HSPCs was sufficient to promote myeloid leukemia, and Imatinib treatment leads to downregulation of Dnmt1 but does not eradicate the disease." (PMID 29955131, 2019).
neuroblastoma (11 papers, 2006 to 2024). Neuroblastoma (NB) is the most common solid, extracranial childhood tumor. "In context to the expression level of DNMT1, we observed significant downregulation in neuroblastoma cells after GW‐9662 treatment (p ≤ 0.05)." (PMID 39679632, 2024). "MHC class I-related gene expression is regulated by DNMT1 in human and mouse neuroblastoma cell lines." (PMID 38136558, 2023). "E3 altered the interaction of SUZ12, LSD1, and DNMT1 with ERα in endometrial cells and altered the interaction of TET2 and DNMT1 with ERα and ERβ in neuroblastoma cells." (PMID 35491423, 2022). "Here, we verified whether retrograde transport is likewise modulated by DNMT1 in neuroblastoma (N2a) cells, in order to assess whether the regulation of retrograde transport is a more general, cellular sub-type independent function of DNMT1." (PMID 32751461, 2020). "To test whether MHC-I genes are regulated by DNMT1 in neuron-like cell lines, we added inhibitors to both human and mouse neuroblastoma cell lines and analyzed gene expression of the MHC-I genes." (PMID 29970123, 2018). "To validate whether a similar regulation of MHC-I genes also existed in mouse cells, we evaluated the expression of H2 genes in mouse N2a neuroblastoma cell lines upon 72 h of treatment with the inhibitor of DNMT1 and DNA methylation 5-aza-2-deoxycytidine (5-aza)." (PMID 29970123, 2018). "To determine this, we used different concentrations (E:T ratios) of DNMT inhibitor with CIK cells and found that a high DNMT1 concentration was required to significantly increase the cytotoxic capacity of CIK cells in neuroblastoma cells." (PMID 39679632, 2024).
oral cancer (11 papers, 2008 to 2024). "Our findings revealed that targeting DNMT1 in oral cancer cells resulted in near-complete genome-wide DNA hypomethylation, triggering the dual attenuation of PI3K-AKT and CDK2-Rb and collaborative phosphorylation of GSK3β." (PMID 38755637, 2024). "The shRNA-specific DNMT1 knockdown was employed to target DNMT1 on oral cancer cells in vitro, as was the use of DNMT1 inhibitors." (PMID 38755637, 2024). "In the present data, knockdown of DNMT1 or DNMT3B restored the expression of TIMP3 in the oral cancer cell lines." (PMID 31624299, 2019). "Of the 125 oral cancer tissues assayed for DNMT3b and DNMT1 using IHC analysis, 76 (61%) gave DNMT3b positive immunoreactivity but only 36% (45/125) with DNMT1 positive staining." (PMID 24625449, 2014). "Besides, the coexistence of DNMT1 overexpression and genome-wide hypomethylation in oral cancer cells may reflect that, given the low maintenance efficacy of DNA methylation, the upregulation of DNMT1 functions as a self-compensatory mechanism to maintain DNA methylation equilibrium." (PMID 38755637, 2024). "From our microarray data, we also found that DNMT1, DNMT3A and DNMT3B were overexpression in oral cancer." (PMID 32238162, 2020).
Alzheimer disease (10 papers, 2013 to 2024). A progressive, neurodegenerative disease characterized by loss of function and death of nerve cells in several areas of the brain leading to loss of cognitive function such as memory and language. "DNMT1 is upregulated in the spared nerve injury-induced NP rat models, and inhibition of DNMT1 potentiates M2 polarization of microglia in Alzheimer’s disease (AD)-related NP." (PMID 36183073, 2022). "In Alzheimer’s disease, there are evidences of decreased 5mC levels and DNA methyl transferase 1 (DNMT1) in the hippocampal and temporal brain region." (PMID 33962636, 2021). "Furthermore, we confirmed previous findings obtained in a cohort of 100 Alzheimer’s disease individuals and matched controls, showing that elevated plasma Hcy levels in the AD subjects were linked to reduced methylation levels of several genes in blood DNA, including DNMT1." (PMID 31817852, 2019). "In Alzheimer’s disease brains, and in vitro studies, we have found qualitative and quantitative deficits in transport into the nucleus of DNA methyltransferase 1 (DNMT1) and RNA polymerase II (RNA pol II), accompanied by their abnormal sequestration in the cytoplasm." (PMID 23308199, 2013). "Notably, DNMT1 and other methylation factors are decreased in Alzheimer’s disease brain tissue, which could lead to passive demethylation." (PMID 38326859, 2024). "Developmental Pb exposure not only altered DNA methylation in both specific gene level and global genome level in brain of Alzheimer’s disease model, but also could affect the expression of DNA methyltransferase 1(DNMT1) and DNA methyltransferase 3a (DNMT3a) in hippocampus." (PMID 28107465, 2017). "It is important to determine whether lactobacillus inhibits senescence by decreasing DNMT1, m1A, m6A, TDP-43, GADD45, MMP-13, and ADAMTS1, and increasing TET2, 3MST, H2S and TIMPs in RED and Alzheimer’s disease." (PMID 39456478, 2024). "The most statistically significant transcription factors were STAT3 (Signal Transducer and Activator of Transcription 3) involved in focal adhesion, DNMT1 (DNA Methyl Transferase 1), and PPARA (Peroxisome Proliferator-Activated Receptor Alpha) involved in Alzheimer’s disease." (PMID 34836168, 2021).
chronic myeloid leukemia (10 papers, 2017 to 2025). "The effects of all three compounds for chronic myeloid leukemia (CML) were conducted in such a way that specifically evaluated changes of expression for DNMT1 and CDKN1A as well as the expression of tumor suppressor genes PTEN and RARB." (PMID 40004944, 2025). "For that purpose, we turned to publically available ENCODE Chip-seq and RNA-seq data sets for human Chronic Myeloid Leukemia (CML) (K562) and human embryonic stem cells (H1-hESCs) displaying the status of H3K27Ac, H3K4Me1, H3K4Me3 and MYC for the genomic loci of DNMT1, DNMT3A and DNMT3B." (PMID 29100357, 2017). "From previous studies, expression of DNMT1 and CDKN1A showed a negative regulation mechanism on chronic myelogenous leukemia." (PMID 33133123, 2020). "Moreover, in chronic myeloid leukemia blast cells, the long noncoding RNA MEG3 interacted with multiple proteins in a large complex comprising DNMT1, JAK2, TYK2, STAT3, and HDAC155." (PMID 32895373, 2020).
Cognitive impairment (10 papers, 2017 to 2023). Abnormal cognition is characterized by deficits in thinking, reasoning, or remembering. "Analysis of self-perceived cognitive impairment revealed that patients with the A allele of DNMT1 rs2162560 had significantly lower odds of cognitive impairment in the concentration ability domain (OR = 0.45, 95% CI: 0.25–0.82, P = 0.01)." (PMID 31601979, 2019). "The established association between DNMT1 SNPs and behavioral disorders could explain why we observed an association between DNMT1 rs2162560 and self-perceived cognitive impairment but not other domains of objective cognitive impairment." (PMID 31601979, 2019).
diabetic retinopathy (10 papers, 2017 to 2025). "However, intervention of good glycemia directly with DNA methylation inhibitors (Azacytidine or Dnmt1-siRNA), prevented Mfn2 and Mlh1 hypermethylation, and ameliorated retinal dysfunction and diabetic retinopathy." (PMID 32313015, 2020). "There also remains a possibility that reduction in further progression of diabetic retinopathy by Aza or Dnmt1-siRNA supplementation during the reversal phase could be due to regulation of mtDNA methylation itself." (PMID 32313015, 2020). "Previous research has demonstrated that DNMT1 could activate the PI3K/Akt/mammalian target of rapamycin (mTOR) pathway in diabetic retinopathy)and 3,6-dihydroxyflavone (3,6-DHF), an effective DNMT1 inhibitor, suppresses the PI3K/Akt/mTOR pathway in breast carcinogenesis." (PMID 36183073, 2022).
lung adenocarcinoma (10 papers, 2011 to 2026). A carcinoma that arises from the lung and is characterized by the presence of malignant glandular epithelial cells. "And HNF1A-AS1 has also been reported to mediate the binding of DNMT1 to E-cadherin in lung adenocarcinoma." (PMID 29100339, 2017). "In general, downregulation of ZEB1, RECK, TGFBR2 and BMPR2, as well as upregulation of CDK4, CCNE2, EZH2 and DNMT1 has been shown in lung adenocarcinoma and/or squamous cell carcinoma." (PMID 27588394, 2016). "Evaluation of the IHC scores showed that expression of both DNMT1 and Survivin was significantly higher in lung adenocarcinoma than that in normal lung tissues." (PMID 27177222, 2016). "In contrast, a positive correlation between Survivin and DNMT1 (r = 0.453, P = 0.045) was observed, consistent with our IHC analysis of Survivin and DNMT1 in lung adenocarcinoma." (PMID 27177222, 2016). "To confirm the positive correlation between Survivin and DNMT1, we then retrospectively examined the expression of DNMT1 and Survivin in a set of tissue sections consisting of 61 patients with lung adenocarcinoma." (PMID 27177222, 2016). "In lung adenocarcinoma (LUAD), elevated ACh levels promote migration and invasion via the α5‐nAChR/DNA methyltransferase 1 (DNMT1)/fragile histidine triad (FHIT) axis." (PMID 41415714, 2025). "Menin expression is inversely correlated with RAS expression in lung adenocarcinomas, and KRAS increases DNA methylation at the MEN1 promoter by upregulating DNMT1/3B and increasing DNMT1 recruitment to the menin promoter." (PMID 39336822, 2024). "Overall, our clinical analyses suggest that elevated expression of DNMT1 significantly correlates with increased Survivin in NSCLC, especially lung adenocarcinoma." (PMID 27177222, 2016).
ovarian tumors (10 papers, 2012 to 2023). "Conversely, increased expression of EZH2 and DNMT1 in ovarian tumors was associated with decreased infiltration of CD8+ T cells and worse prognosis." (PMID 27199994, 2016). "Conversely, increased expression of EZH2 and DNMT1 in ovarian tumors was associated with decreased infiltration of CD8+ T cells and poor prognosis." (PMID 27793053, 2016). "Enhancer of zeste homolog 2 (EZH2)-mediated histone H3K27me3 and DNMT1-mediated DNA methylation suppress the ovarian tumor production of Th1-inducing chemokine, CXCL9 and 10, and decrease TIL in TME." (PMID 36991099, 2023). "In the present study, we for the first time immunohistochemically determined the expression of DNMT1, DNMT3a, and DNMT3b proteins in benign and malignant ovarian tumor tissues." (PMID 22768205, 2012). "The present study suggests that re-expression of miR-148a and miR-152 by epigenetic therapy aiming to DNMT1 suppression might resensitize resistant ovarian tumors to conventional chemotherapy." (PMID 33680048, 2020). "Furthermore, treatment of ovarian tumors with EZH2 and DNMT1 inhibitors increased the efficacy of tumor-associated antigen-specific CD8+ T cells in response to PD-L1 inhibition." (PMID 27199994, 2016). "Furthermore, treatment of ovarian tumors with EZH2 and DNMT1 inhibitors increased the efficacy of tumor-associated antigen-specific CD8+ T cells in response to inhibition of the PD-1: PD-L1 checkpoint." (PMID 27793053, 2016).
acute lymphoblastic leukemia (9 papers, 2006 to 2025). Leukemia with an acute onset, characterized by the presence of lymphoblasts in the bone marrow and the peripheral blood. "TQ has also reduced DNMT3A, DNMT3B, and DNMT1 expression in acute lymphoblastic leukemia cells (Jurkat cells)." (PMID 37375831, 2023). "6-TG can facilitate the proteasome-mediated degradation of DNMT1 and reactivate epigenetically silenced genes in acute lymphoblastic leukemia cells." (PMID 33194583, 2020). "Changes in DNMT1 promoter methylation were also observed in peripheral blood DNA samples from patients with acute lymphoblastic leukemia (ALL) and were linked to the DNMT1 expression pattern in the patients." (PMID 31817852, 2019). "In acute lymphoblastic leukemia (ALL) cell lines, and xenograft models, we observed increased DNMT1, and KMT2A expression in response to decitabine‐induced demethylation." (PMID 39754404, 2025). "TQ also has decreased the expression of DNMT1, DNMT3A, and DNMT3B in Jurkat T-cell acute lymphoblastic leukemia cells." (PMID 34959687, 2021).
adenoma (9 papers, 2013 to 2025). A neoplasm arising from the epithelium. "As such, our study systematically analyzed the expression patterns of DACH1 and DNMT1 across normal tissues, adenomas, and adenocarcinomas by integrating clinical samples with data from the TCGA database." (PMID 40370966, 2025). "A progressive decrease in DACH1 expression and a concomitant increase in DACH1 promoter methylation and DNMT1 expression were observed from normal mucosa to adenoma and adenocarcinoma tissues." (PMID 40370966, 2025). "Overall, DNMT1 expression exhibited a progressive increase at both the protein and mRNA levels during the transition from normal mucosa to adenoma and adenocarcinoma." (PMID 40370966, 2025). "IHC results demonstrated a progressive increase in DNMT1 protein expression along the normal-adenoma-adenocarcinoma sequence." (PMID 40370966, 2025). "We demonstrated that DACH1 expression progressively decreased from normal colorectal mucosa to adenoma and adenocarcinoma tissues, while its methylation level and DNMT1 expression exhibited the opposite trend." (PMID 40370966, 2025). "In contrast, DNMT1 protein expression demonstrated an opposite trend, with the lowest expression in normal mucosa, moderate expression in adenoma, and the highest levels in carcinoma tissues." (PMID 40370966, 2025). "A progressive decrease in DACH1 expression from normal mucosa to adenoma to adenocarcinoma were observed, while DNMT1 expression showed a corresponding increase, demonstrating an inverse relationship in both protein and mRNA levels." (PMID 40370966, 2025). "PCR analysis of DNMT1 mRNA expression further confirmed a stepwise increase in expression levels from normal mucosa to adenoma and adenocarcinoma tissues." (PMID 40370966, 2025). "-Decreases cellular proliferation, DNMT1 protein expression, and p16 promoter methylation in adenomas." (PMID 26840292, 2016). "Dnmt-1: healthy control (HC) vs UC patients, p < 0.001; adenoma vs UC and dysplasia, p = 0.09; adenocarcinoma vs UC and cancer, p = 0.008." (PMID 26862732, 2016). "Notably, signs of severe mucosal damage, including epithelial pseudostratification and adenoma-like lesions, were occasionally observed in P7–P21 Dnmt1 homozygous mutant mice (scored by pathologist)." (PMID 26420038, 2015). "The progressive increase in DNMT1 expression drives the epigenetic silencing of DACH1 via promoter methylation, facilitating the transition from adenoma to carcinoma." (PMID 40370966, 2025). "Normal mucosa, adenoma, and carcinoma tissues obtained from the same patient were used to detect the expression of DACH1 and DNMT1 during CRC progression by IHC." (PMID 40370966, 2025). "Semi-quantitative scoring of DNMT1 staining revealed that the proportion of cases with negative staining (−) was highest in normal mucosa and significantly reduced in adenoma and adenocarcinoma tissues, with no cases observed in adenocarcinoma." (PMID 40370966, 2025). "Since E-cadherin expression is known to be a critical step in the progression of well differentiated adenoma to invasive carcinoma, HNF1A-AS1 may mediate the binding of DNMT1 to E-cadherin which decreases the E-cadherin and induces EMT." (PMID 25863539, 2015). "In addition, immunohistochemical analysis on sections of normal and adenoma tissue found up-regulation of EED and DNMT1 protein in adenoma." (PMID 23408899, 2013). "As an E2F target, Dnmt1 (DNA methytrasferase 1) showed differential expression throughout tumor progression (expression fold changes in PyMT tumors vs. FVB controls during hyperplasia, adenoma/MIN, early carcinoma, and late carcinoma are 2.0, 2,5, 2.3, and 3.2 (FDR < 0.05), respectively)." (PMID 28212608, 2017).
Infertility (9 papers, 2012 to 2026). "In humans, the DNA methyltransferase 1 (DNMT1) is restricted to male germ cells (pachytene SPC and round SPT), and infertile patients showing round SPT maturation arrest also show a specific DNMT1 loss in these cells." (PMID 24324492, 2013). "In addition, significant correlations were foundbetween sperm concentration and motility as well as DNMT1 and DNMT3B proteins levels in the infertile individualswith varicocele (P<0.05)." (PMID 34455713, 2021). "Furthermore, since DNMT1 and HDAC1 are two critical genes for proper epigenetic modification and development, changes to these genes may impact the results of maturation, fertilization, and embryonic development in PCOS mice, ultimately leading to infertility." (PMID 38102694, 2023).